CXCR4 (C-X-C motif chemokine receptor 4)
Diseases named in the same sentence as CXCR4 in open-access papers (continued):
Sharing a sentence is not in itself a finding about the gene and the disease.
tumor (continued). "This elevation in CXCR4 expression of neutrophils in tumor-bearing animals was almost completely abolished on antibody blockade of the aging-promoting chemokine receptor CXCR2." (PMID 34876407, 2021). "It has been reported that the CXCL12/CXCR4 axis is related to tumor progression, angiogenesis, metastasis, and survival." (PMID 33747044, 2021). "Based on in vitro studies, the resulting protein NPs were internalized by CXCR4+ cells and inhibited the growth of tumor cells." (PMID 34361141, 2021). "In preclinical trials, anti-CCL2 in combination with BRAF-targeted therapy reduced tumour sizes, as did anti-CXCR4 peptides when used alongside PD-1, and both demonstrated a reduction in MDSCs and T-regs." (PMID 34830780, 2021). "Immunotherapy responders showed distinct B cell gene expression with enhanced anti-tumor immune signaling in the form of CXCR4 signaling, cytokine receptor interaction and chemokine signaling pathways." (PMID 33708214, 2021). "The present study shows that these impaired pDC in the pre-tumor microenvironment can also promote cancer cell proliferation and migration via NF-κB-activated CXCR-4 overexpression by a paracrine mechanism." (PMID 33854604, 2021). "CXCR4 is expressed on the surface of many tumor cells and in the cytoplasm, and the ligand stromal cell-derived factor 1 (SDF-1) thereof is a significant α-type chemokine, which is mainly produced by stromal cells." (PMID 34733839, 2021). "Pretreatment with AMD3100, the specific antagonist of CXCR4, consistently reduced the homing of hMSCs towards primary tumor." (PMID 33838662, 2021). "Accordingly, from immunofluorescence results, CXCR4 mainly expressed inside the tumor region, which further indicated a crucial role of CXCR4 in the regulation of actin and ECM remodeling in the tumor microenvironment (TME)." (PMID 34676245, 2021). "Tumor-infiltrating-pDC-conditioned medium from OSCC patients significantly promoted tumor cell proliferation and invasion, which was at least partly mediated via enhancing the CXCR-4 expression of tumor cell." (PMID 33854604, 2021). "GSCs expressing CXCR4 have been identified in close proximity to tumor vascular capillaries, strengthening the idea that these cells are involved in vascular remodeling in the tumor." (PMID 33391498, 2021). "Tumor infiltrating MDSCs are known to express high levels of CXCR4 and to migrate towards a SDF-1 gradient." (PMID 34417915, 2021). "High binding affinity to mCXCR4 of the DV1-k-(DV3) scaffold and high expression of CXCR4 in mouse liver make evaluation of the clinical potential of this new class of CXCR4-targeting radiotracers in tumor mouse models difficult." (PMID 34683912, 2021). "The results confirm clinical observations of CXCR4 S338X showing prolonged MAPK signaling compared to frameshift mutations and present with higher tumor burden." (PMID 33273682, 2021). "And more interestingly even, was the fact that the vasculature of both tumor models expressed similar amounts of CXCR4." (PMID 34793563, 2021). "The CAF-mediated CXCL12/CXCR4 axis plays a key role in tumor cell proliferation, invasion, and migration." (PMID 34447750, 2021). "A review of the literature showed a paucity of reports involving IL-33/ST2 or SDF1/CXCR4 signaling to target TME for tumor progression." (PMID 34298657, 2021). "Further analysis revealed that CXCR4-null KPC tumor cells were more invasive and exhibited higher proliferative and migratory phenotypes than wildtype KPC cells." (PMID 34298706, 2021). "CXCL12/CXCR4 signaling can also enhance tumor progression by attracting pro-tumoral immunosuppressive immune cells." (PMID 34503058, 2021). "Among tumor-related genes (CXCR4, FOS, DUSP10), FOS is a member of the FOS gene family and plays a regulatory role in cell proliferation, differentiation, and apoptosis." (PMID 35111153, 2021). "We observed percentage of CXCR4 expressing BCSCs followed an increasing trend with the distance from the primary tumor site." (PMID 34778599, 2021).
tumor (continued). "CAFs also enhance cancer growth by increasing the secretion of stromal derived factor-1 (SDF-1) which directly stimulates the expression of cognate receptor, CXCR4, that initiates angiogenesis and tumor cell motility." (PMID 34821729, 2021). "Tumour uptake positively correlated with CXCR4 expression with 26-fold greater uptake in CXCR4 positive vs. negative tumours (9.20 ± 2.08 vs. 0.33 ± 0.03%ID/g)." (PMID 34436693, 2021). "Although CXCR4 and ACKR3 can be co-expressed on tumour cells, CXCR4 tends to be more highly expressed on GSCs, whereas ACKR3 is detected at higher levels on differentiated tumour cells." (PMID 33803414, 2021). "CXCR-4 (C-X-C chemokine receptor type 4), also known as fusin or CD184, like VEGFA, is closely associated with tumor formation and angiogenesis in different cancers." (PMID 34298612, 2021). "SDF-1 is advocated to fascinate CXCR4-expressing tumor cells to specific metastatic tissues, and high levels of SDF-1 are found in organs commonly affected by tumor metastasis, such as the lung." (PMID 33406809, 2021). "Lexiscan was used to pharmacologically increase BBB permeability, AMD3100 was utilized to target CXCR4 overexpressed on tumor cells, and a neutrophil elastase (NE)-cleavable peptide was used for controlled drug release at the tumor." (PMID 34716900, 2021). "The upregulated level of CXCR4 in the tumor tissues was significantly correlated with poor prognosis in patients with HCC." (PMID 33889573, 2021). "Because CXCR3 activation has a role in promoting the anti-tumor response in PD-1 immunotherapy, a better understanding of the ligands that bind CXCR3 variants (CXCR3A, CXCR3B) and competing receptors (CXCR4, CXCR7) is needed." (PMID 33676416, 2021). "The overexpression of CXCR4 in cancer directly affects the chemotaxis of tumor cells to the SDF-1 gradient." (PMID 33710803, 2021). "CXCR4 also plays important roles in the development, invasion, angiogenesis, epithelial–mesenchymal transition and maintenance of stemness of tumour cells, and targeting CXCR4 is a potential therapeutic strategy for treating malignant tumours." (PMID 34050566, 2021). "The interactions facilitated by CXCL12/CXCR4/CXCR7 axes seem to be strongly linked to CSC “stem”-like features, tumor progression, and metastasis promotion." (PMID 33530455, 2021). "The tumors growing in IFNβ-deficient mice showed enhanced infiltration of pro-tumor neutrophils expressing the pro-angiogenic factors VEGF and MMP9 and the homing receptor CXCR4 that is usually upregulated in senescent neutrophils." (PMID 34572138, 2021). "Existing reports suggest that CXCR4 is frequently expressed by malignant tumor and is imperative for vascularization, tumor growth, cell migration, and metastasis pertaining to poor prognosis." (PMID 33414415, 2021). "Hence, we hypothesized one explanation for the variability of spleen CXCR4 expression in solid tumor patients could potentially be an activated state of spleen, through tumor-related effects, associated with suppression of anti-tumor immunity and potentially adverse clinical outcomes." (PMID 34417915, 2021). "It is possible that both U2932 and SuDHL8 models are equally metastatic in relation to vascular CXCR4 dominantly affecting invasion and extravasation, but differently regulated by other factors that promote tumor growth." (PMID 34793563, 2021). "Expression of the tumor cell homing marker CXCR4 changes between different tumor areas and between cell lines." (PMID 33467498, 2021). "PET imaging of [18F]MCFB, a tumor-penetrating CXCR4-targeted small molecule, was used to provide whole-tumor CXCR4 readouts." (PMID 34793563, 2021). "Compelling evidence indicates that CXCR4 regulates tumor EMT together with the c-MET signaling pathway." (PMID 34568309, 2021). "CXCL12 and CXCR4 interactions are also involved in tumor growth and metastasis by induction of angiogenesis and expression of CXCR4 on metastatic cancer cells." (PMID 34072818, 2021).
tumor (continued). "CXCL-12 is a chemokine that acts through CXCR4 and plays an essential role in tumor invasion and metastasis in numerous cancer types." (PMID 33390169, 2021). "The CXCR4 expression on tumor cells is upregulated by hypoxia and by other angiogenic factors, which are capable of directing the trafficking of normal and malignant cells expressed high levels of CXCL12 and CD44 43-45." (PMID 34093792, 2021). "Patients with a CXCR4-high CRC, according to meta-analyses, are likely to show a poorer prognosis, poorer tumor differentiation, and a higher risk of metastasis." (PMID 34335790, 2021). "The SDF-1α/CXCR4 axis plays an important role in the mobilisation and homing of circulating tumour cells." (PMID 33919589, 2021). "B cells selectively promote lymph node metastasis through pathogenic IgG production that activates the HSPA4-binding protein ITGB5 and the Src/NF-κB pathway in tumor cells for CXCR4/SDF1α-axis-mediated metastasis." (PMID 33937018, 2021). "A xenograft assay validates the tumor growth-impeding effect and inhibition of CXCR4/SHH/GLI1 signaling cascade after ETV4 depletion." (PMID 34052833, 2021). "Remarkably, in all three xenograft animal models, irrespective of surface or intracellular expression of CXCR4, CXCR4 knockdown resulted in a significant reduction of tumor growth compared to their respective control." (PMID 33966046, 2021). "Accordingly, exposure to CXCL2 or to the supernatant of SCC VII or 4T1 tumor cells induced a significant increase in the surface expression of CXCR4 on neutrophils isolated from the peripheral blood of wild-type (WT) mice." (PMID 34876407, 2021). "Upon inhibition of CXCR4, CD8 TIL were released from the TNC‐rich stroma, now accessing and killing the tumor cells causing reduced tumor growth and subsequent metastasis." (PMID 33988305, 2021). "We examined the inhibitory effect of rhosin on CXCR4 expression, and tumor cell migration and invasion in B16BL6 cells." (PMID 33406809, 2021). "Their results showed that overexpression of CXCR4 was related to tumor depth (P < 0.01), lymph node status (P < 0.01), tumor node metastasis stage (P < 0.01), and histological type (P = 0.03)." (PMID 33710803, 2021). "Persistent high expression of CXCR4 after chemoradiotherapy predicts tumor recurrence and poor prognosis." (PMID 33710803, 2021). "CXCR4 positive tumor cells metastasize to organs with high expression of CXCL12, such as lymph nodes, liver, lungs, and bone marrow." (PMID 33710803, 2021). "In pooled analyses, significant associations were found between positive or high or strong expression of CXCR4 and T stage ≥3 (P = 0.0001), and positive or high or strong expression of CXCR4 and left side primary tumor localization (P = 0.0186)." (PMID 34209026, 2021). "During previous studies in solid tumor patients using [68Ga]Pentixafor, we observed a wide variance not only of tumor, but also spleen CXCR4 expression." (PMID 34417915, 2021). "On the other hand, angiogenesis-related molecular signaling pathway activation was found in vivo and in vitro with increased VEGF and CXCR4 mRNA levels, which coincided with the higher vascular density observed in tumor tissues in vivo." (PMID 34479611, 2021). "The interaction of CXCL12 with CXCR4 and the subsequent signal transduction plays an important role in tumor progression and metastasis." (PMID 34833360, 2021). "It has been suggested that disseminated tumor cells can use the same physiological mechanisms as those used by hematopoietic stem cells (HSCs) homing to bone, involving primarily the CXCR4/CXCL12 axis." (PMID 33671469, 2021). "In our research, CXCR4 was observed to be mainly expressed inside the tumor region but rarely in the peri-tumor." (PMID 34676245, 2021).
tumor (continued). "The authors described that GSC are recruited by tumor EC through Stromal Cell-Derived Factor 1 (SDF-1)/C-X-C Chemokine Receptor Type 4 (CXCR4) signaling and generate pericytes mainly through activation of the TGF-β pathway." (PMID 34361013, 2021). "One in vivo study suggested that a subpopulation of CRC, the CD133(+)CXCR4(+) colorectal cancer tumor-initiating cells (Co-TICs), presented a higher tumor formation capacity in a humanized orthotopic mouse model." (PMID 34335790, 2021). "SDF-1/CXCR4 is a key signal axis that mediates the communication between tumor cells and stromal cells." (PMID 34733839, 2021). "PC-derived chemokine CXCL12 (SDF-1) can trigger the EGF/CSF-1 paracrine invasion loop to mediate the co-migration of TAM and tumor cells, after binding to its receptor CXCR4 on both TAMs and tumor cells (process ➁)." (PMID 34179005, 2021). "Analysis of clinical samples validated the overexpression of the 4 genes (SQSTM1, BIRC5, NRG3, and CXCR4) in tumor tissues relative to paired normal tissues, consistent with bioinformatic findings." (PMID 34484469, 2021). "Tumor cells that maintain CXCR4 overexpression, but lack CXCL12 expression, can be directionally transferred to target organs with high levels of CXCL12 secretion." (PMID 33710803, 2021). "In bone metastases, CXCL12 and CXCR4 can be produced or expressed by a broad panel of cell types such as osteoblasts, osteocytes, CAFs, neutrophils, tumor cells, and adipocytes." (PMID 34064859, 2021). "Mechanistically, both miRNA-34a and miR-200c directly target HIF1-α and subsequently downregulate VEGFR, MMP9 and CXCR4, although combined miRNA-34a and miR-200c delivery suppresses mouse xenograft tumor development as effectively as individual delivery." (PMID 33673143, 2021). "CXCR4 is the most commonly expressed receptor in human cancers and is a surface marker that serves to identify CSCs of many tumor types." (PMID 33530455, 2021). "Increasing studies suggested that CXCL12/CXCR4 axis played pivotal roles in tumor growth and development." (PMID 34123594, 2021). "Apart from tumor growth and angiogenesis, the CXCL12/CXCR4 axis is widely known for its role in predisposing the metastatic niche." (PMID 34503058, 2021). "As stated in the preceding section, the CXCL12/CXCR4 axis plays a crucial role in bone metastasis and the interaction between tumor cells and bone cells." (PMID 34064589, 2021). "Chemokine CXCL12 and its specific receptor CXC chemokine receptor 4 (CXCR4) constitute the biological axis of CXCL12/CXCR4, which are involved in inflammatory reaction, tumor formation, and other disease." (PMID 33880887, 2021). "In this article, it was demonstrated that exosomes upregulated CXCR4 expression in MDSCs, indicating the function of CXCL12-CXCR4 axis in promoting the attraction and retention of MDSCs into the tumor microenvironment." (PMID 34659412, 2021). "We next examined the correlation of CXCR4 expression with RCC patient prognosis in the 100 ccRCC tumor specimens." (PMID 34804954, 2021). "Silencing XBP1 and CD44 reduced tumor cell invasion and adhesion to HBMECs, whereas silencing CXCR4 decreased the tumor cells migration." (PMID 34093792, 2021). "We examined the expression of CXCR4 in these tissue samples and found that CXCR4+ tumor cells tended to be increased in DPP-4i–treated tumors." (PMID 36860286, 2021). "CM of IL-17RB OE PSCs induced CXCR4 expression, contributing to tumor growth, invasion, and metastasis." (PMID 34771503, 2021). "The diminished angiogenic response was also seen in tumours established from Mmp-9 knockout cells or tumours treated with CXCR4 inhibitor AMD3100." (PMID 33803414, 2021). "PDC/PDCX-based and pathological analyses of RCC uncovered that NRN1 and its co-expressing molecule CXCR4 are positively associated with RCC patient prognosis and their silencing substantially suppresses PDC viability and PDCX tumor growth." (PMID 34804954, 2021).
tumor (continued). "Given its pre-eminent role in the context of tumor cell growth as well as metastasis, the C-X-C motif chemokine receptor 4 (CXCR4) has attracted a lot of interest in nuclear oncology." (PMID 34885030, 2021). "Consistently, the immunohistochemistry (IHC) was performed, and the results validated that CXCR4 positively regulated Ki67 protein levels in mice tumor tissues." (PMID 34180759, 2021). "MSCs can increase angiogenesis through the induction of ERK1/2 and p38 MAPK pathways, which enhance the expression of VEFG and CXCR4 in tumor cells." (PMID 34112253, 2021). "CXCR4/CXCR7 antagonism should prevent the development of metastases by interfering with tumor cell growth, migration and chemotaxis and favoring the frequency of T cells in TME." (PMID 33937018, 2021). "The overexpression of CXCR4 in tumor tissue is related to tumor proliferation, tumor invasion, increased risk of metastasis, and poor survival outcomes." (PMID 33710803, 2021). "CXCR4+ cells isolated from NSCLC lines were able to form the tumor spheres in vitro, had self-renewal capacity, demonstrated radiation resistance in vitro." (PMID 34203877, 2021). "The radiotracer displayed tumor uptake specific to CXCR4 expression with good tumor-to-muscle (9.5 ± 1.7) and tumor-to-blood (6.3 ± 1.8) ratios." (PMID 34500609, 2021). "The discovery involves tumor-initiating cancer stem cells (CSC) of CXCR4 expression which is conducive to CXCR4 in resistance to treatment, recurrence, metastasis and poor clinical outcome." (PMID 34322132, 2021). "This factor then binds to its chemokine receptors CXCR4 and CXCR7, causing monocytes from bone marrow to enter the tumor, thus producing new blood vessels in the tumor and leading to recurrence." (PMID 34568049, 2021). "CXCR4 plays an important role in tumor biological behaviors, such as growth, metastasis, angiogenesis, and cancer cell–microenvironment interactions." (PMID 34676245, 2021). "Mediating its effects by binding to its major corresponding receptor, CXCR4, CXCL12 is implicated in inflammatory responses, autoimmune diseases, T cell homing, angiogenesis, CAFs activation, EMT, tumor progression, metastasis, and therapy resistance." (PMID 34064859, 2021). "An oral CXCR4 antagonist, X4P-001, improves the efficacy of checkpoint inhibitor therapy and modulates tumor infiltrating immune cells by disrupting the CXCL12-CXCR4 axis." (PMID 34806028, 2021). "CXCR4 signaling and its effect on tumor cell stemness, self-renewal and infiltration can also be inhibited by the miR-302–367 cluster which consists of five different microRNAs (miR-302a, miR-302b, miR-302c, miR-302d, miR-367)." (PMID 34203660, 2021). "CXCR4 antagonists play an important role in sensitizing tumor cells to chemotherapy, and existing imaging agents targeting CXCR4 have the potential to guide and monitor cancer treatment." (PMID 33710803, 2021). "Recently, it was shown that combined PD-1 and CXCR4 inhibitors treatment on PDAC tissues can increase the tumor cell apoptosis and CD8+ T cell migration into the juxta-tumoral compartment." (PMID 34638560, 2021). "The C-X-C motif chemokine receptor 4 (CXCR4) is overexpressed in various cancer stem/progenitor cells via activation of the epithelial-mesenchymal transition (EMT) program to facilitate tumor cell aggressiveness in the premetastatic niche." (PMID 34070538, 2021). "The novel CXCR4-targeting radioprobes were further evaluated in wild-type mice and a hCXCR4-expressing tumor mouse model." (PMID 34683912, 2021). "It inhibits CRI critical pathway and downstream cytokines expression through targeting CXCR4 amongst others, resulting in decrease of tumor growth." (PMID 33579381, 2021). "Numerous studies have demonstrated a role for CXCR4 in mediating tumour cell proliferation, through the use of CXCR4 antagonists AMD3100, peptide R and PRX177561, or by downregulating CXCR4 expression." (PMID 33803414, 2021).